ANXA2 (annexin A2)
Diseases named in the same sentence as ANXA2 in open-access papers (continued):
Sharing a sentence is not in itself a finding about the gene and the disease.
tumor (continued). "We further studied the correlation between ANXA2 expression and tumor stage and found that the expression of ANXA2 in tumor stages 1–3 was significantly higher than that in normal tissues." (PMID 38658569, 2024). "The ANXA2 gene can interact with various genes and participate in multiple signaling pathways, regulating the proliferation cycle of tumor cells." (PMID 39350574, 2024). "ANXA2 can affect the growth and development of tumor cells and regulate the migration, invasion, and adherence of tumor cells." (PMID 39057791, 2024). "In recent years, increasingly more studies have focused on the relationship between ANXA2 and tumor microenvironment." (PMID 38519766, 2024). "Accordingly, preclinical studies have been evaluating the anti-tumor efficacy of Annexin A2-targeting therapy, alone or in combination with anti-PD-1 antibodies." (PMID 38519766, 2024). "ANXA2 is an important member of the annexin family and is expressed on the surface of various tumor cells." (PMID 39697329, 2024). "Previous evidences have indicated ANXA2 to be correlated with suppressive tumor microenvironment, especially correlated with decreased T-cell activation." (PMID 38519766, 2024). "In the current study, ANXA2 expression was also found upregulated in tumor tissues, especially in high-grade or high-stage RCC." (PMID 38519766, 2024). "The impact of ANXA2 on the tumor microenvironment was assessed by RNA-sequencing, flow cytometry and immunohistochemistry in two localized RCC datasets (ZS-HRRCC, n = 40; TCGA-KIRC, n = 530)." (PMID 38519766, 2024). "When it comes to liver oncology, silencing of ANXA2 arrested the cell cycle in vitro, inhibited tumor growth in vivo, and suppressed the invasion, migration, and tumorigenic potential of HCC cells." (PMID 39594718, 2024). "Previous studies have confirmed that ANXA2 influences tumour angiogenesis, and we then determined ANXA2 expression after FGF19 treatment." (PMID 37782406, 2024). "Tumor growth curve results showed that ANXA2 knockdown inhibited the size and growth rate of tumors in vivo." (PMID 38658569, 2024). "ANXA2 was found to be essential for T cell to T cell interactions, and the upregulation of ANXA2 leads to decreased T-cell activation in tumor microenvironment." (PMID 38519766, 2024). "ANXA2 has been found to take part in tumor immune escape, and therapeutic resistance of immunotherapy." (PMID 38519766, 2024). "The relationship between ANXA2 and tumor-infiltrating immune cells was evaluated by H&E or IHC in RCC." (PMID 38519766, 2024). "Certain preclinical studies have shown that inhibiting ANXA2 or disrupting its interactions with key molecules can suppress tumor growth, invasion, and metastasis, as well as increase the cancer cells’ sensitivity to treatment in various cancers." (PMID 39594718, 2024). "Accordingly, preclinical studies have been evaluating the anti-tumor efficacy of ANXA2-targeting therapy." (PMID 38519766, 2024). "The research on Annexin A2 in tumours is currently active, and studies on its role in pathogen infection are increasing." (PMID 37482693, 2023). "It showed that ANXA2 played a general role in most types of cancer, demonstrating its importance in tumor development promotion and led to poor prognosis through epithelial-mesenchymal transition, cancer drug resistance and other pathways." (PMID 36713082, 2023). "The surface protein annexin A2, a calcium-binding cytoskeletal protein localized on various tumor cells, has been shown to be a receptor for CTX on the surface of human cancer cell lines and to be involved in cell migration, invasion, and adhesion." (PMID 37444498, 2023). "Clinically, Annexin A2 has significant implications in the development of tumours, inflammation, and other diseases." (PMID 37482693, 2023). "We expect that Cy7‐YW7 has the potential to address the need to facilitate complete PAAD tumor resection by targeting ANXA2‐overexpressing tumor cells." (PMID 36453020, 2023).
tumor (continued). "One of the highest expressed genes is ANXA2, a gene involved in tumor heterogeneity and cancer progression." (PMID 37685859, 2023). "Recent studies have identified ANXA2 expression in several cancers where it promotes tumor progression via proliferation, migration, epithelial-mesenchymal transformation (EMT), invasion and stem cell formation." (PMID 36750863, 2023). "When TCGA and GTEx databases were combined together, the expression of ANXA2 was higher in BRCA compared with corresponding normal tissues, the average expression levels of ANXA2 were 9.675 and 9.545 in tumor and normal tissues, respectively." (PMID 36713082, 2023). "Based on the TCGA database alone, the expression of ANXA2 was lower in BRCA compared with corresponding normal tissues, the average expression levels of ANXA2 were 9.675 and 9.887 in tumor and normal tissues, respectively." (PMID 36713082, 2023). "Specifically, we identified two CD8+ TEM clusters occupying a large proportion of CD8+ T cells, with T07 ANXA2+ TEM enriched in tumor sites and T08 GZMK+ TEM enriched in ascites." (PMID 37488416, 2023). "At 28 h post-injection (hpi), we observed that the relative growth of the tumor within the yolk sac was much lower after injection of shANXA2 MDA-MB-231 cells as compared to control cells, suggesting reduced survival of ANXA2-deficient cells." (PMID 38092984, 2023). "We show that the genetic inhibition of ANXA2 prevents tumor invasion and metastasis processes when these cells are injected in mice or zebrafish." (PMID 38092984, 2023). "The GSEA was conducted to further explore the ANXA2-related pathways in tumorigenesis and tumor development." (PMID 36713082, 2023). "To investigate the role of ANXA2 in tumor progression, we labelled control and shANXA2 MDA-MB-231 cells with a luciferase reporter and injected the cells into the tail vein of NOD SCID mice and RAG mice." (PMID 38092984, 2023). "To further investigate the specific mechanism by which ANXA2 affects the inflammatory response, we found that ANXA2 is able to stimulate tumour cell proliferation by altering STAT3 phosphorylation levels." (PMID 36932468, 2023). "The implications of JICD1 and ANXA2 should be investigated under distinct conditions, such as tumor vasculature or other types of cancer." (PMID 37834227, 2023). "We further constructed the nomograms based on ANXA2 and other independent prognosis factors (age, gender, grade, stage, and anatomic neoplasm subdivision), in order to demonstrate ANXA2 is important to predict the survival probabilities of PAAD patients." (PMID 36453020, 2023). "Despite that phosphorylated ANXA2 expression is more specific to tumor compared to the unphosphorylated form, our findings show that both FITC‐ and Cy7‐YW7 also possess a high specificity to PANC‐1 cells." (PMID 36453020, 2023). "JICD1 overexpression increased tumor propagation, whereas ANXA2 knockdown hindered tumor propagation 69 days after intracranial injection." (PMID 37834227, 2023). "Fetuin-B, a biomarker of COPD, and annexin A2, which is recognized as a multiple tumour marker, were coidentified in five out of six treated rats’ self-control samples on D3." (PMID 37753171, 2023). "To further verify that the binding between YW7 and ANXA2 on tumor cells, we further knocked down of ANXA2 on PANC‐1 cells using small interfering RNAs (siRNAs)." (PMID 36453020, 2023). "Tyr23 Phosphorylation of ANXA2 by Src tyrosine kinase promotes proliferation, migration, and invasion of tumor cells." (PMID 36229838, 2022). "Precisely, various strategies have already been developed successfully targeting ANXA1 and ANXA2 functions, which have shown efficacy on various preclinical tumor models." (PMID 36247003, 2022). "ANXA2 participation was frequently reported in tumour cell adhesion, proliferation, invasion, metastasis and tumour neovascularisation." (PMID 35163852, 2022).
tumor (continued). "Spatial plot analysis revealed that ANXA2 protein content was predominantly located at the edge of malignant tumor compartment, adjacent to the tumor stroma." (PMID 36377658, 2022). "Serum EV annexin A2, which directly promotes angiogenesis, as shown by an in vivo Matrigel plug assay, correlated strongly with tumour grade and poor overall and disease-free survival in TNBC." (PMID 35053279, 2022). "The other 4 (100%) with high sEV-derived AnxA2 mRNA expression responded well to the chemotherapy with significant downstaging of the tumor." (PMID 36612209, 2022). "Otherwise, ANXA2 participates in cell survival, proliferation, invasion and metastasis, thus acting as a regulator of tumor growth and progression, suggesting that ANXA2 is a target in cancer treatment." (PMID 36362054, 2022). "The results showed that ANXA2 is predominantly expressed by tumor cells (cytokeratin+, CK+) in both the PL and LLC models, with very little staining evident in macrophages (F4/80+)." (PMID 36377658, 2022). "Our study indicated that cell surface expression of AnxA2 is very high in T24 cells derived from a high-grade tumor." (PMID 36428758, 2022). "Simultaneously, high expression of ANXA2 had been confirmed to play a pivotal role in tumor cell adhesion, proliferation, apoptosis, invasion, and metastasis." (PMID 35211410, 2022). "ANXA2 is detected in a variety of malignancies and regulates apoptosis, metastasis, cell proliferation, invasion, adherence, and tumor neovascularization, all of which are important in tumor progression." (PMID 36589842, 2022). "All 3 (100%) patients with high AnxA2 protein expression in sEVs responded well with significant downstaging of the tumor to neoadjuvant chemotherapy." (PMID 36612209, 2022). "Both NSCLC tumor lysates and ANXA2 protein induced ARG1 mRNA expression by approximately 2-fold in naive HDNs." (PMID 36377658, 2022). "The expression of AnxA2 was significantly upregulated in BLCA tumor tissues compared to normal bladder tissues (p < 0.0001)." (PMID 36428758, 2022). "Several studies have shown that the AnxA2 expression is correlated with high tumor grade and stage and poor survival of cancer patients." (PMID 36428758, 2022). "Several studies have reported that overexpression of AnxA2 activates several signaling pathways involved in tumor proliferation, invasion, migration, angiogenesis, and metastasis." (PMID 36428758, 2022). "Two Rh2 targets are directly relevant to the tumor’s ability to invade, annexin A2 (ANXA2), and matrix metalloproteinase (MMP)." (PMID 35163891, 2022). "elucidated one mechanism of PDA metastasis formation: Sema3D can bind to PlxnD1 on the surface of PDA tumor cells in the extracellular space by the regulation of its autocrine function control of AnxA2." (PMID 36713527, 2022). "In CRC, CAF-derived LINC00659 directly binds to the tumor suppressor miR-342-3p in cancer cells, enhances the expression of ANXA2, which is involved in the EMT process, and promotes the development of CRC." (PMID 35359397, 2022). "Moreover, ANXA2 Tyr 23 phosphorylation is implicated in the initiation of endothelial-mesenchymal transition (EndMT) and regulation of cell motility, and may contribute to tumor progression." (PMID 36120574, 2022). "Different studies have reported relationships of ANXA2 with poor or good prognosis depending on the tumor location or the studied cohort." (PMID 36247003, 2022). "Lastly, we were able to demonstrate that this axis is relevant to human disease by reproducing the key findings using human peripheral blood neutrophils, NSCLC tumor lysates, and recombinant human ANXA2 protein." (PMID 36377658, 2022). "Targeting tumor neovascularization and extracellular matrix is also a strategy, and recent studies have shown that Annexin A2 (ANXA2) has been detected in OC." (PMID 36261831, 2022).
tumor (continued). "Since the tumor cells usually recapitulate embryonic cells, Sadashiv and colleagues investigated the ANXA2 expression in developing renal tissues and adult RCCs." (PMID 36120574, 2022). "ANXA2 is a calcium-regulated membrane-binding protein produced by a wide range of cell types, including epithelial, dendritic, trophoblast, and tumor cells, as well as monocytes and macrophages." (PMID 35203500, 2022). "Overexpression (OE) of YES1 increases, while knockdown (KD) of YES1 or ANXA2 decreases GC cell invasion and migration in vitro and tumor growth in mouse models." (PMID 33941853, 2021). "Meanwhile, ANXA2 was positively related to the infiltration of tumor-related macrophages, regulatory T cells and myeloid-derived suppressor cells." (PMID 34675316, 2021). "Annexin A2 (ANXA2) is a calcium phospholipid binding protein that is present on the surface of various tumor cells." (PMID 33406648, 2021). "ANXA2 promotes tumor proliferation by upregulating several oncogenes, such as β-catenin, cyclin D1, oncostatin M receptor (OSMR), and c-Myc26–29." (PMID 33712571, 2021). "Otherwise, ANXA2 participate in cell survival, proliferation, invasion and metastasis, thus acts as a regulator in tumor growth and progression, which support that ANXA2 is a proposing target in cancer treatment." (PMID 33995636, 2021). "Although data from p11 KO-mice often supports findings that AnxA2/p11-dependent plasmin generation is involved in tumour progression, it should be noted that p11 has plenty of other tumourigenic functions that appear rather unrelated to AnxA2." (PMID 33810523, 2021). "The results found that ANXA2 was highly expressed in OSCC tissues, and was associated with the TNM stage, tumor differentiation, lymph node metastasis and poor survival of OSCC patients." (PMID 33658625, 2021). "In mouse models for pancreatic ductal adenocarcinoma (PDAC), AnxA2 KO-animals displayed a substantial reduction in PDAC tumour invasion and metastasis." (PMID 33810523, 2021). "Recently, LS301 has been shown to target the phosphorylated phospholipid-binding protein Annexin A2, which is an abundant post-translational modification of the Annexin A2 preferentially found in tumor microenvironments." (PMID 34277418, 2021). "Increased researchers have focused on roles of ANXA2 on proliferation, migration, invasion and metastasis of tumor cells." (PMID 33995636, 2021). "Extracellular ANXA2 accelerates angiogenesis and contributes to the formation of an immune microenvironment that promote tumor metastasis." (PMID 34599143, 2021). "Western blot analysis showed that compared with adjacent non-tumor tissues, the protein expression level of ANXA2 in cancer tissues increased (P < 0.05)." (PMID 34120429, 2021). "Patients with high ANXA2 expression in their tumors exhibited shorter tumor‐free survival than those with low ANXA2 expression in their tumors." (PMID 34047479, 2021). "Targeting Annexin A2 (ANXA2), a protein previously implicated in GBM invasion and progression, miR-1 also decreased the release of EVs by the tumor, in turn leading to decreased progression and angiogenesis." (PMID 34298912, 2021). "In summary, the secretion of tumor-derived exosomal ANXA2 depends on intracellular calcium levels and novel autophagy-mediated secretion." (PMID 34599143, 2021). "pT stage, tumor size and high ANXA2 expression were also nearly significant predictors for IVR although the impact was not significant statistically." (PMID 34048174, 2021). "Along these lines, a cyclic octapeptide labeled with a near-infrared dye selectively binding phosphorylated AnxA2, which is highly expressed in a wide range of solid tumours, provides opportunity for tumour imaging and localized drug delivery." (PMID 33810523, 2021). "A study based on immunohistochemistry provide evidence of ANXA2 presence in cancer samples, ANXA2 expression was increased in human tumor tissues." (PMID 33995636, 2021).
tumor (continued). "MiR-206 has also directly targeted the oncogenes KRAS and annexin a2 (ANXA2), acting as a tumor suppressor in various types of cancer by blocking cell cycle progression, cell proliferation, migration, and invasion." (PMID 34900997, 2021). "PLGA nanoparticles loaded with Annexin A2-Curcumin conjugate at a dose of 20 mg/kg every alternate day for 32 days, decreased the tumor volumes by 44% ± 5.2% along with remarkable inhibition of neovascularization." (PMID 35582033, 2021). "Studies showed that down-regulating of ANXA2 inhibiting tumor cell invasion and metastasis, and overexpression of ANXA2, promote the invasion and metastasis capability of tumor cells 52, 64-69." (PMID 33995636, 2021). "In recent years, most studies have shown that ANXA2 played an important role in tumor cell growth, adhesion and metastasis." (PMID 33658625, 2021). "Our studies demonstrate that ANXA2 plays a critical role in promoting GC cell proliferation and metastasis, the expression of ANXA2 is positively correlated with tumor invasion, regional metastasis, relapse and the poor overall survival of GC patients." (PMID 33941853, 2021). "For RFS, presence of ascites, tumor number ≥ 2, presence of microvascular invasion and microsatellite distribution of tumors, high Annexin A2 expression, AFP and AST > upper limit of normal were associated with RFS by univariate analysis." (PMID 34575275, 2021). "Alternatively, treatment of tumour cells with a cytosol-targeting small peptide that binds to intracellular AnxA2 showed a reduced capacity to colonize lungs in several mouse models." (PMID 33810523, 2021). "Annexin A2 (ANXA2) is a calcium-binding cytoskeleton protein located on the extracellular surface of endothelial cells and in various types of tumor cells." (PMID 34771640, 2021). "At present, numerous studies have shown that CD147 can interact with varieties of molecules to regulate the occurrence, development, invasion, and metastasis of tumor, including Annexin A2 (ANXA2), VEGFR-2, MCT1, integrin-β1, CD44, cyclophile." (PMID 35003362, 2021). "The expressions of YES1 and ANXA2 were significantly related to tumor invasion, regional metastasis and GC relapse during 3-year follow-up period." (PMID 33941853, 2021). "Annexin A2 isoform 2 (ANXA2) has been reported to play an important role in tumor migration and invasion, and L-lactate dehydrogenase A chain (LDHA) and PKM1 have both been reported to be closely related to tumor glycometabolism." (PMID 33495406, 2021). "Among these genes, ANXA2 belongs to the Annexin family and is reported to work in several tumor cellular processes, such as cell cycle regulation, angiogenesis, tumor invasion, and progression." (PMID 34026819, 2021). "Anti-ANXA2 antibody have been proved to serve as a suppressor in tumor invasion and metastases 59, 70-75." (PMID 33995636, 2021). "ANXA2 is a calcium-dependent phospholipid binding protein and is expressed in a wide spectrum of cancers, and exerts profound effects on tumor cell adhesion, proliferation, apoptosis, invasion and metastasis as well as tumor neovascularization." (PMID 34048174, 2021). "ANXA2 perform important roles in tumor progression, including cell survival, proliferation, migration, invasion and metastatic." (PMID 33995636, 2021). "In Qiu’s study, an elevated ANXA2 level resulted in the upregulation of the proportion of Treg cells and promoted tumor immune escape." (PMID 34484309, 2021). "The Annexin A2 (ANXA2)-S100A10 heterotetramer is an important plasminogen receptor, associated with tumor invasion and metastasis." (PMID 32867190, 2020). "AnxA2 immunostaining was mainly localized at the membrane and with less extent in the cytoplasm of the tumor cells in TNBC specimens." (PMID 33374917, 2020). "Regarding the bone compartment, ANXA2 is expressed in bone cells and acts as a chemotactic factor promoting the tumor tropism to this homing organ." (PMID 32197509, 2020).